TGFB1 (transforming growth factor beta 1)
Diseases named in the same sentence as TGFB1 in open-access papers (continued):
Sharing a sentence is not in itself a finding about the gene and the disease.
thoracic aortic aneurysm (41 papers, 2012 to 2025). An aneurysm formed in the wall of the proximal portion of the descending aorta proceeding from the arch of the aorta. "The TGFβ1 pathway is central to syndromic thoracic aortic aneurysm and dissection, typified by Marfan syndrome." (PMID 33082445, 2020).
small cell lung carcinoma (40 papers, 1993 to 2025). Small cell lung cancer (SCLC) is a highly aggressive malignant neoplasm, accounting for 10-15% of lung cancer cases, characterized byrapid growth, and early metastasis. "Nine human small-cell lung cancer cell lines were treated with transforming growth factor beta 1 (TGF-beta 1)." (PMID 8180008, 1994).
epilepsy (39 papers, 2017 to 2026). A brain disorder characterized by episodes of abnormally increased neuronal discharge resulting in transient episodes of sensory or motor neurological dysfunction, or psychic dysfunction. "Biallelic loss-of-function mutations in TGFB1 result in very early-onset inflammatory bowel disease and CNS dysfunction associated with epilepsy, brain atrophy, and posterior leukoencephalopathy." (PMID 35625943, 2022). "Although the brain pericyte-derived TGF-β contributes to the upregulation of BBB functions, suppression of TGFβ1 indicates improvement in epilepsy." (PMID 34209145, 2021).
Chagas disease (38 papers, 2012 to 2025). A parasitic infection caused by Trypanosoma cruzi. "Still, it is important to understand if polymorphisms in the TGFB1 gene are also implicated in Chagas disease susceptibility in Brazil, as the Brazilian population presents a different genetic background from that of other Latin American countries." (PMID 29670670, 2018). "A previous work has already associated the TGFB1 polymorphism at codon 10 to Chagas disease susceptibility in Colombian and Peruvian cohorts." (PMID 29670670, 2018). "This analysis confirmed that allele C and genotypes TC and CC at codon 10 of the TGFB1 gene were significantly increased in Chagas disease patients." (PMID 29670670, 2018). "Similar findings were observed for the genotype T/C at codon +10 of the TGFB1 gene: patients heterozygous or homozygous for this allele also had an increased risk of Chagas disease." (PMID 29670670, 2018). "However, the distribution of polymorphisms in the TGFB1 gene among Chagas disease clinical forms was similar." (PMID 29670670, 2018). "We tested whether TGFB1 polymorphisms could be associated with Chagas disease susceptibility and severity in a Brazilian population." (PMID 29670670, 2018). "Moreover, the frequencies of the “T” allele in −509 C/T and of the “C” allele in +10 T/C TGFB1 polymorphisms were higher in patients with Chagas disease." (PMID 29670670, 2018). "Thus, we analyzed the association between TGFB1 SNP and Chagas disease independently of the region the patient was born." (PMID 29670670, 2018). "Therefore, −509 C>T and +10 T>C TGFB1 polymorphisms are associated with Chagas disease susceptibility in a Brazilian population." (PMID 29670670, 2018). "Furthermore, we also wanted to study the association of polymorphisms in the TGFB1 gene with the different clinical forms of Chagas disease and with the severity of the cardiac form." (PMID 29670670, 2018). "Thus, −509 C/T and +10 T/C TGFB1 polymorphisms were associated with Chagas disease susceptibility in this Brazilian population." (PMID 29670670, 2018). "In the present study, we aimed to check if this association could also be observed in the Brazilian population and to explore if differences in TGFB1 polymorphism distribution could be observed between patients with the indeterminate and cardiac forms of Chagas disease." (PMID 29670670, 2018). "During the acute and chronic phases of Chagas disease, TGFβ1 is involved in the invasion of cardiac fibroblasts and myocytes, intracellular parasite life cycle, regulation of inflammation and immune response, fibrosis, and heart remodeling." (PMID 33804922, 2021). "Very interestingly, five SNP in the TGFB1 gene of known or suggested functional significance (−988 C>A, −800 G>A, −509 C>T, +10 T>C, and +263 C>T) were studied in a Peruvian and a Colombian population seropositive for Chagas disease versus seronegative." (PMID 29670670, 2018). "We found a significant difference in the distribution of the TGFB1 −509 C/T and +10 T/C variants between noninfected subjects and patients with Chagas disease." (PMID 29670670, 2018). "Genotypes TC and CC at codon +10 of the TGFB1 gene were also more frequent in Chagas disease patients than in noninfected subjects." (PMID 29670670, 2018). "Genotypes CT and TT at position −509 of the TGFB1 gene were more frequent in Chagas disease patients than in noninfected subjects." (PMID 29670670, 2018). "The genotypes CT and TT at position −509 of the TGFB1 gene were more frequent in patients with Chagas disease than in noninfected subjects (P = 0.0003)." (PMID 29670670, 2018). "This is the first study to demonstrate that the frequencies of the polymorphic CT and TT genotypes at position −509 and the TC and CC genotypes at codon +10 of the TGFB1 gene were increased in Brazilian Chagas disease patients compared to noninfected subjects." (PMID 29670670, 2018).
diabetic retinopathy (38 papers, 2012 to 2025). "Transforming growth factor β1 (TGFβ1) is a proinflammatory cytokine that has been implicated in the pathogenesis of diabetic retinopathy (DR), particularly in the late phase of disease." (PMID 33334029, 2020). "DNA hypomethylation of NLR family pyrin domain containing 3 (NLRP3) is associated with increased risk of diabetic retinopathy, and that of TNFα, TGFβ1 and MCP-1 is considered responsible for its increased expression in the serum of patients with proliferative diabetic retinopathy." (PMID 36672234, 2023). "Collectively, these findings suggest that TGFβ1, which is compensatory upregulated in aging populations, could be an important causative and disease-propagating factor in diabetic retinopathy pathogenesis." (PMID 35740425, 2022). "TGFβ1 is elevated in total serum of diabetic patients and its levels correlate with diabetic retinopathy disease progression." (PMID 35740425, 2022). "The main drawback of our study is the limited number of patients in each group, and a bigger longitudinal study would strengthen our data and the conclusions regarding the prognostic value of TGFβ1 in diabetic retinopathy." (PMID 33334029, 2020). "It has also been shown that the hypomethylated state of the promoters of NLRP3, TGFβ1, MCP-1, and TNFSF2 may increase the risk of developing diabetic retinopathy." (PMID 39883715, 2025). "The transforming growth factor beta 1 (TGFB1) is a pro-inflammatory cytokine that plays a key role in the mechanisms of angiogenesis and breakdown of the blood-retina barrier, which are implicated in the pathogenesis of diabetic retinopathy (DR)." (PMID 37418683, 2023). "Indeed, a previous study reproducing in vitro diabetic retinopathy reported a reduction of Transforming Growth Factor beta 1 (TGF-β1) in human retinal pigment epithelial cells cultured in high glucose and treated with OTX008." (PMID 38169923, 2023). "Human retinal pericytes (HRP) have also been used to test the effects of TGFβ1 and TGFβ2 in the induction of BIGH3 protein and apoptosis, suggesting that the increase of the BIGH3 causes loss of retinal pericytes during early events in diabetic retinopathy." (PMID 35072165, 2021). "In conclusion, our data have strengthened the hypothesis that TGFβ1 would be a biomarker and pharmacological target of diabetic retinopathy." (PMID 33334029, 2020). "Furthermore, elevated TGFβ1 levels may be responsible, at least in part, for both microvascular and senescent phenotypes in diabetic retinopathy." (PMID 35740425, 2022). "Another key effector factor in diabetic retinopathy may be TGFβ1." (PMID 35740425, 2022). "Furthermore, we show that TGFβ1 induces, besides VEGF, the release of many essential cytokines that play a role in the progression of diabetic retinopathy." (PMID 35740425, 2022). "Besides alterations in TGFβ1 and VEGF, senescence in retinal cells may contribute to diabetic retinopathy pathogenesis." (PMID 35740425, 2022).
Duchenne muscular dystrophy (37 papers, 2011 to 2026). Duchenne muscular dystrophy (DMD) is a neuromuscular disease characterized by rapidly progressive muscle weakness and wasting due to degeneration of skeletal, smooth and cardiac muscle. "CTGF is overexpressed in skeletal muscle of individuals with Duchenne muscular dystrophy and has been shown to interact with TGFβ1 to produce an increase in the expression of ECM proteins." (PMID 34707569, 2021). "Fibronectin was described as a seric biomarker of Duchenne muscular dystrophy (DMD), and its expression during fibrosis has been shown to be regulated by TGFB1 and CTGF, whose expression patterns follow those of FN1 in our study." (PMID 32670085, 2020).
lupus nephritis (37 papers, 2010 to 2026). Glomerulonephritis in the context of systemic lupus erythematosus. "The aim of this study was to compare genetic variants from the TGFB1, IRF5, STAT4 genes and TRAF1-C5 locus with susceptibility to IgAN and lupus nephritis in two Swedish cohorts." (PMID 20479942, 2010). "Allelic frequencies of STAT4, IFR5, TRAF1-C5 and TGFB1 polymorphisms in lupus nephritis against SLE patients without nephritis." (PMID 20479942, 2010). "The observed increase in the abundance of miR-221-5p may be a homeostatic mechanism to counteract an increase in the expression of laminin-1, which has been described to replace laminin-11 in glomerular basement membrane as a result of overproduction of TGFB1 in patients with lupus nephritis." (PMID 27835701, 2016).
ulcer (37 papers, 2010 to 2025). "For TGF-βR I, SMAD2, and TGFβ-1, 4 of 6 patients showed the same expression patterns; mRNA expression of TGF-βR I and SMAD2 was lower in skin around ulcers than in normal skin, while the expression of TGFβ-1 expression was higher." (PMID 28687753, 2017). "In the hamsters with improvement of their ulcers, the expression levels increased 0.011 ± 0.017 times for PDGF, 17.5 ± 2.4, for EGF, 0.01 ± 0.03 for FGF, and 2.1 ± 0.1 for TGFβ1." (PMID 30333964, 2018). "It is not fully known why these defective transitions occur in ulcers but one factor may be due to a lack of critical cytokines such as TGFβ1 in the wound environment." (PMID 34778380, 2021). "Given that TGFβ increases the ARG activity at the expense of NOS activity, this lack of TGFβ1 in the ulcer macrophages translates into an impaired transition from the tissue debridement to the tissue repair stage." (PMID 34778380, 2021).
pneumonia (35 papers, 2012 to 2025). An acute, acute and chronic, or chronic inflammation focally or diffusely affecting the lung parenchyma, caused by an infection in one or both of the lungs (by bacteria, viruses, fungi, or mycoplasma.). "Disease ontology (DO) analysis showed that TGFβ1 and hypoxia‐de‐regulated lncRNAs were associated with many diseases including IPF and pneumonia." (PMID 31925944, 2020). "Exogenous TGFb-1 does not exacerbate alcohol-associated pneumonia." (PMID 37886455, 2023). "Acute pneumonia increased the expression of TNF-α, IFN-γ, IL-6, IL-2 and IL-17 genes, and decreased the expression of Foxp3, IL-10, and TGFβ1 genes in lung tissue homogenate of mice." (PMID 35782123, 2022).
radiation pneumonitis (35 papers, 2008 to 2025). Inflammation of the lung due to harmful effects of ionizing or non-ionizing radiation. "Activated TGFβ1 has a superior capacity in predicting radiation pneumonitis (RP) risk and plays a vital role in the development of radiation‐induced pulmonary fibrosis (RIPF)." (PMID 38239077, 2024). "We found that activated TGFβ1 had better performance for radiation pneumonitis (RP) risk prediction by detecting activated and total TGFβ1 levels in patient serum." (PMID 38239077, 2024). "Single nucleotide polymorphisms (SNPs) in TGFβ1 can predict the risk of radiation pneumonitis (RP) in patients with non-small cell lung cancer (NSCLC) after definitive radiotherapy." (PMID 28574846, 2017). "Transforming growth factor beta 1(TGF‐β1) polymorphism was associated with radiation pneumonitis (RP) susceptibility, but their results have been inconsistent." (PMID 27470220, 2016). "The results from our study suggest, for the first time, that the TGFβ1 rs1982073 variant genotypes may be useful as a genetic biomarker to help physicians tailor the treatment according to the patient’s risk of radiation pneumonitis and DM." (PMID 23840350, 2013).
sarcoidosis (35 papers, 2014 to 2026). Sarcoidosis is a multisystemic disorder of unknown cause characterized by the formation of immune granulomas in involved organs. "Interestingly, among highly active sarcoidosis patients, hypoxia may promote a pro-inflammatory response and a profibrotic response (TGFβ1, PDGF-BB) with SERPINE1 secretion associated with human lung fibroblast migration inhibition." (PMID 36289785, 2022). "For example, here, among other genes, STAT1, IL10RA, and PTEN were underexpressed in sarcoidosis CD14 monocytes compared to controls while CXCR4, ATG12, HIF1A, CCR1, and IER3 were overexpressed, consistent with the effects of TGFB1 signaling." (PMID 33363531, 2020).
benign prostatic hyperplasia (34 papers, 2010 to 2026). A non-cancerous nodular enlargement of the prostate gland. "Finally, we also analyzed gene expression profiles of prostate stromal cells (PrSC), which were driven to transdifferentiate into premature senescent myofibroblasts by TGFβ1, a process considered a hallmark of the aging human prostate, leading to benign prostatic hyperplasia." (PMID 20883526, 2010). "TGFβ1 is a major cytokine in inflammation that is as a key player in the regulation of stromal differentiation and proliferation in benign prostatic hyperplasia." (PMID 28904557, 2017). "Transforming growth factor-β1 (TGFβ1)-induced differentiation into and the activation of myofibroblasts have been regarded as critical events in benign prostatic hyperplasia (BPH); however, the underlying mechanisms of BPH pathogenesis remain unclear." (PMID 31694982, 2019).
co-infection (34 papers, 2012 to 2025). "While Ifnb1 was only upregulated following GAS infection, Tgfb1 was downregulated after GAS infection as well as co-infection." (PMID 36365071, 2022). "Notably, TGF-β signaling (TGFB1-TGFBR1-TGFBR2) was extinguished during HIV-mono infection yet reappeared in co-infection, whereas IL16-CD4 and CD40LG-(ITGAM/ITGB2) interactions disappeared with HIV-mono and did not recover, underscoring stage-specific rewiring of T-cell communication networks." (PMID 41394852, 2025). "The relationship between immune exhaustion markers (PD-1/PD-L1) and apoptotic markers such as Fas/FasL, TGFβ1, TNF-α, and Th1/Th2 cytokines are not clearly delineated in HBV/HIV coinfection." (PMID 30815625, 2019).
IgA nephropathy (34 papers, 2005 to 2025). "The rs2241715, in linkage disequilibrium with rs1800469 in the present and another IgA nephropathy study, is located in the TGFB1 DNase I hypersensitive‐intron 1, a known regulatory region." (PMID 38970443, 2024).
lymphedema (34 papers, 2009 to 2025). Excess fluid collection in tissues, causing swelling. "One of the primary factors involved in lymphedema-associated fibrogenesis is TGFβ-1, rendering this molecule a logical target for the prevention of lymphedema progression." (PMID 38612716, 2024). "Separate studies have corroborated these findings, noting correlation between IL-10, TNF-α, and TGFβ-1 levels and lymphedema-related factors following lymph node transfer." (PMID 38612716, 2024). "Secondary lymphedema is a common complication of cancer treatment, and previous studies have shown that the expression of transforming growth factor‐beta 1 (TGF‐β1), a pro‐fibrotic and anti‐lymphangiogenic growth factor, is increased in this disease." (PMID 35652284, 2022). "The significant increase in subcutis thickness, T-cell density, collagen deposition, and TGFβ1 expression suggests that the combined cervical lymphatic injury protocol mediates chronic changes that are consistent with postsurgical lymphedema seen in humans." (PMID 31797883, 2019).
nephritis (33 papers, 2005 to 2025). Inflammation of renal tissue. "In control mice with nephritis, Ctgf, Tgfb1, Acta2, Fn1, and Itgav mRNA expressions in the glomeruli were increased compared with control mice without nephritis." (PMID 28191821, 2017). "Tgfb1, Acta2, Fn1 and Itgav mRNA expression in the glomeruli was increased in control mice with nephritis, and this increase was reduced in Pdgfra-CTGF cKO mice with nephritis." (PMID 28191821, 2017). "Glomerular gene expression of Tgfb1, α-smooth muscle actin (Acta2), fibronectin (Fn1) and integrin αv (Itgav) was increased in control mice with nephritis and this increase was reduced in Rosa-CTGF cKO mice with nephritis." (PMID 28191821, 2017). "Interestingly, TGFβ1 was over-expressed at late stages of anti-GBM nephritis, which might correlate to crescent formation occurring at the same time." (PMID 23441175, 2013). "To test this hypothesis we compared the genotype, allelic and haplotype frequencies from IRF5, STAT4 and TRAF1-C5 polymorphisms between IgAN patients and healthy controls, and SLE patients with and without nephritis, from TGFB1 polymorphisms between SLE patients and healthy controls." (PMID 20479942, 2010). "In addition to the increases in the expression levels of fibrotic makers such as Tgfβ1, Acta2, and Fn1, the glomerular mRNA expression of MCP-1 (Ccl2) and F4/80 (Adgre1) is increased in the control mice with anti-GBM nephritis, and this increase is reduced in the Rosa-CTGF cKO mice with nephritis." (PMID 30123390, 2018). "Expression of Fn1, Acta2, Tgfb1, Adgre1 or Ccl2 was tended to be reduced in Rosa-CTGF cKO mice with nephritis, but not significant." (PMID 28191821, 2017).
Cachexia (32 papers, 2012 to 2026). Severe weight loss, wasting of muscle, loss of appetite, and general debility related to a chronic disease. "Mice with TGFβ1‐knockout appeared normal within approximately 3 weeks after birth, but they died soon after due to severe wasting syndrome caused by defects in angiogenesis and hematopoietic function." (PMID 38299307, 2024). "The TGFβ signaling pathway has been implicated in development of cachexia, and its superfamily members including TGFβ-1 and Growth Differentiation Factor (GDF-15) have been found to be elevated in plasma of pre-cachectic and cachectic cancer patients experiencing weight loss." (PMID 28177923, 2017). "TGFβ1 and TGFβ3 levels were up-regulated by cachexia in AT, as well in the isolated adipocytes." (PMID 28288584, 2017). "The importance of TGFβ signaling in the immune system is highlighted by the finding that mice lacking TGFβ1 develop a severe lethal wasting syndrome within 3 weeks of birth, associated with a mixed inflammatory cell infiltration and lesions in different organs including the heart and lungs." (PMID 22703233, 2012). "However, the dominant secreted cytokine of M2 ATMs derived from the cachexia model was Vegf but not Tgfb1, indicating that those belonged to the M2d subtype under the cancer cachexia." (PMID 38657734, 2024).
HIV-1 infection (32 papers, 2006 to 2025). The type species of lentivirus and the etiologic agent of acquired immunodeficiency syndrome (AIDS). "To study the potential role of LysRS in regulating USF2 in HIV-1 infected cells, we examined the mRNA transcript levels of TERT, PTPN6 and TGFb1 when the function of pS207-LysRS was blocked during HIV-1 infection." (PMID 37933844, 2023). "In JurkatS207A cells, the transcription of USF2 target genes PTPN6 and TGFb1 was suppressed during HIV-1 infection compared with JurkatWT cells (top)." (PMID 37933844, 2023).
sarcopenia (32 papers, 2011 to 2026). Progressive decline in muscle mass due to aging which results in decreased functional capacity of muscles. "Inducible neutrophil-specific TGFβ1 deletion prevented age-related sarcopenia." (PMID 41890838, 2026).